ADAM10 (ADAM metallopeptidase domain 10)
Diseases named in the same sentence as ADAM10 in open-access papers (continued):
Sharing a sentence is not in itself a finding about the gene and the disease.
osteosarcoma (4 papers, 2014 to 2025). A usually aggressive malignant bone-forming mesenchymal neoplasm, predominantly affecting adolescents and young adults. "The main purpose of this study is to explore the effects of ADAM10 on osteosarcoma cell functions and the underlying molecular mechanisms." (PMID 32256208, 2020). "We investigated the ADAM10 expression (active form and pro form) in one osteoblast (hFOB 1.19) and six osteosarcoma cells (Saos-2, SW1353, HOS, U-2OS, MG63, and 143B) through western blot and real-time PCR, respectively." (PMID 32256208, 2020). "We found that the expression of ADAM10 was relatively high in osteosarcoma cells compared with that in osteoblast." (PMID 32256208, 2020). "Overall, the ADAM10 expression in six osteosarcoma cells was higher than that in the osteoblast hFOB1.19 at both protein levels and mRNA levels." (PMID 32256208, 2020). "The effect of ADAM10 on the tumorigenicity of osteosarcoma cells was evaluated in a nude mice model in vivo." (PMID 32256208, 2020). "The biological functions of ADAM10 in osteosarcoma cells were measured by cell counting kit-8 assay, flow cytometry, wound healing assay, and transwell assay." (PMID 32256208, 2020). "Results of western blot and real-time PCR assays showed that ADAM10 expression was significantly decreased in ADAM10-silenced osteosarcoma cells." (PMID 32256208, 2020). "The results reveal that ADAM10 is a downstream target gene of miR-122-5p and miR-122-5p negatively regulated ADAM10 expressions directly in the osteosarcoma cells." (PMID 32256208, 2020). "We demonstrated that the volume and weight were decreased in the ADAM10-silenced osteosarcoma tissues, and ADAM10 knockdown inhibited tumorigenicity of osteosarcoma cells." (PMID 32256208, 2020). "MiR-122-5p-induced inhibition of cell proliferation, migration, and invasion was reversed by overexpression of ADAM10 in osteosarcoma cells." (PMID 32256208, 2020). "Western blot and quantitative real-time PCR were performed to detect the expression of ADAM10 in one osteoblast (hFOB 1.19) and six osteosarcoma cells (Saos-2, SW1353, HOS, U-2OS, MG63, and 143B)." (PMID 32256208, 2020). "Herein we show that ADAM10 was generally expressed in osteosarcoma tumor cells in a condensed and polarized pattern." (PMID 24548763, 2014). "Under 400× magnification, a polarized and condensed expression pattern of cytoplasmic ADAM10 was observed in all cases and stages of osteosarcoma." (PMID 24548763, 2014). "We found that only ADAM10 expression was significantly correlated with tumor progression and osteoblastic osteosarcoma development." (PMID 24548763, 2014). "And we also found that the expression of ADAM10 could promote cell proliferation, migration, and invasion of osteosarcoma." (PMID 32256208, 2020). "Therefore, our findings demonstrate that ADAM10 knockdown suppresses the tumor development and E-cadherin/β-catenin signaling pathway in osteosarcoma tissues." (PMID 32256208, 2020). "Furthermore, we indicate that knockdown of ADAM10 can inactivate E-cadherin/β-catenin signaling pathway, and ADAM10 knockdown inhibit tumorigenicity of osteosarcoma cells in the hypodermis of nude mice." (PMID 32256208, 2020). "Further rescue experiments revealed that ADAM10 overexpression could abrogate the miR-122-5p-mediated inhibition of cell proliferation, migration, and invasion in osteosarcoma cells." (PMID 32256208, 2020). "In this study, we focused on the roles of ADAM10 on the osteosarcoma cells and found that ADAM10 promoted osteosarcoma cell proliferation, migration, and invasion by regulating E-cadherin/β-catenin signaling pathway and ADAM10 knockdown inhibited tumorigenicity of osteosarcoma cells." (PMID 32256208, 2020). "Downregulation of ADAM10 suppressed the tumorigenicity of osteosarcoma cells in vivo." (PMID 32256208, 2020). "ADAM10 promoted osteosarcoma cell growth, migration, and invasion." (PMID 32256208, 2020).
osteosarcoma (continued). "Based on these data, it is reasonable to speculate that ADAM10 may play a role in osteosarcoma cell growth, migration and invasion." (PMID 32256208, 2020). "We first examined the expression of ADAM10 in osteosarcoma tissue chips." (PMID 24548763, 2014). "As a major sheddase of Notch receptors, ADAM10 has been implicated in many types of cancers, but its role in osteosarcoma has not been investigated." (PMID 24548763, 2014). "Although ADAM10 has been found to be upregulated in many cancers, its expression in tumors with mesenchymal origin (particularly osteosarcoma) remains unknown." (PMID 24548763, 2014). "Our results highlight the importance of ADAM10 in the progression of osteosarcoma and suggest that the protein might be a potential therapeutic target in osteosarcoma treatment." (PMID 24548763, 2014). "The number of ADM10+ tumor cells in stages IIA and IIB increased significantly compared with those in stage IA, suggesting that elevated ADAM10 levels in tumor cells might be involved in the progression of osteosarcoma." (PMID 24548763, 2014). "As ADAM10 is a major regulator of Notch signaling via its shedding of Notch receptors, we sought to determine whether increased expression of ADAM10 in osteosarcoma progression would also lead to increased activation of Notch1." (PMID 24548763, 2014). "Furthermore, we explore whether miR-122-5p affected osteosarcoma cell functions by targeting ADAM10." (PMID 32256208, 2020). "In addition, miR-122-5p can target ADAM10 in osteosarcoma cells." (PMID 32256208, 2020). "In addition, the ADAM10 expression increased with the progression of osteosarcoma." (PMID 32256208, 2020). "Therefore, there are maybe some other miRNAs targeting ADAM10 to regulate osteosarcoma progression, which need more explorations in the future." (PMID 32256208, 2020). "Therefore, we deduce that miR-122-5p/ADAM10 axis may also serve as a therapeutic target for osteosarcoma treatment." (PMID 32256208, 2020). "However, to the best of our known, the effects of ADAM10 on cell functions and the underlying molecular mechanisms in osteosarcoma have never been reported." (PMID 32256208, 2020). "However, the role of ADAM10 in osteosarcoma is still unclear." (PMID 24548763, 2014). "The level of ADAM10 in tumor cells significantly increases as osteosarcoma progresses, as well as in osteoblastic osteosarcoma tissue, suggesting that it might play a role in osteosarcoma tumor progression and the pathological development of osteoblastic osteosarcoma." (PMID 24548763, 2014). "In order to determine whether ADAM10 was differentially expressed among different stages of osteosarcoma, ADM10+ tumor cells were counted under 100× ADAM10/DAPI merged images." (PMID 24548763, 2014). "Tissue chip samples from 40 cases of nonmetastatic osteosarcoma were stained for cytoplasmic ADAM10, activated Notch1 and CD31." (PMID 24548763, 2014). "In our present study, we examined the expression of CD31, ADAM10, Notch1 and TRAP in nonmetastatic osteosarcoma tissue chips." (PMID 24548763, 2014). "The goal of our present study was to investigate the expression of ADAM10, Notch1, CD31 and tartrate-resistant acid phosphatase (TRAP) in nonmetastatic osteosarcoma tissue and their respective contributions to tumor progression." (PMID 24548763, 2014). "In addition, multinucleated giant cells in giant cell-rich osteosarcoma were also found to coexpress CD31, ADAM10 and NICD, but were negative for TRAP staining." (PMID 24548763, 2014).
pancreatic adenocarcinoma (4 papers, 2013 to 2023). "Moreover, high expression of ICAM1 and high expression of ADAM10 or ADAM17 was associated with poor clinical outcome in pancreatic adenocarcinoma patients." (PMID 37732732, 2023). "In silico analysis of publically available expression array data indicated overexpression of Fat1 as well as ADAM10 in pancreatic adenocarcinomas." (PMID 24625754, 2014). "Particularly, Fat1 was ranked among the 1% highest overexpressed genes and ADAM10 among the 5% highest overexpressed genes in pancreatic adenocarcinoma in three of five studies, respectively, with overexpression, although less pronounced, also detected in the other two studies." (PMID 24625754, 2014). "In conclusion ADAM10 mediated ectodomain shedding of Fat1 represents a novel mechanism producing a soluble form of this giant protocadherin that appears to be abundantly produced by human pancreatic adenocarcinoma cells in vitro and less so by their normal counterparts." (PMID 24625754, 2014).
Parkinson disease (4 papers, 2016 to 2025). A progressive degenerative disorder of the central nervous system characterized by loss of dopamine producing neurons in the substantia nigra and the presence of Lewy bodies in the substantia nigra and locus coeruleus. "sTREM2, cleavage by ADAM10 or ADAM17 is detected in human cerebrospinal fluid (CSF), and its levels are elevated in CSF of patients with various neurological conditions, such as AD, Parkinson’s disease (PD)." (PMID 40636122, 2025).
renal carcinoma (4 papers, 2014 to 2025). A carcinoma arising from the epithelium of the renal parenchyma or the renal pelvis. "In renal carcinoma context, studies have reported (i) an increased expression of ADAM10 and ADAM17 in renal cancer tissues and cell lines and (ii) that renal cancer cells failed to develop tumours in vivo in the absence of ADAM17." (PMID 24504508, 2014). "However, in a study using the renal carcinoma cell line A498, ADAM10 silencing resulted in the downregulation of E-cadherin protein." (PMID 39995975, 2025). "However, ADAM10 and γ-secretase have numerous substrates such as Notch and c-Met known to play important roles during renal cancer development." (PMID 24504508, 2014). "In normal PTE cells, MUC1, ADAM10 and ADAM17 proteins were undetectable whereas all of them were expressed in RCC4, RCC10 and 786-O renal cancer cell lines." (PMID 24504508, 2014). "In kidney cancer cell lines, LPA-induced HB-EGF shedding and subsequent EGFR transactivation is mediated by ADAM10 in ACHN cells, whereas ADAM17 is responsible for these events in human renal carcinoma cells (CaKi2) and Human kidney carcinoma cell line (A498)." (PMID 25356505, 2014). "Together, these findings indicate that blockage of MUC1-C nuclear localization either through inhibition of ADAM10 and PSEN1 expression or direct MUC1-C inihibitor are enough to significantly decrease renal cancer cell invasiveness." (PMID 24504508, 2014). "In contrast, MUC1, ADAM10 and ADAM17 were absent in PTE cells while they were expressed in renal cancer cell lines." (PMID 24504508, 2014).
tauopathies (4 papers, 2013 to 2024). "We were able to detect a specific ADAM10-generated tau peptide fragment in serum, as well as highly elevated levels in the brains of the Tg4510 mice, a model of tauopathies known to demonstrate tau aggregation." (PMID 23717682, 2013).
Type 1 Diabetes (4 papers, 2015 to 2022). "Serum ADAM10 level was measured in type 1 diabetes and control subjects, and the association with serum soluble RAGE was determined." (PMID 26325204, 2015). "Serum ADAM10 level is increased in type 1 diabetes and there is a significant association between ADAM10 and serum cRAGE level." (PMID 26325204, 2015). "Serum ADAM10 was an independent determinant of serum cRAGE in patients with type 1 diabetes (p<0.01), and accounted for 21% of the variation in serum cRAGE." (PMID 26325204, 2015). "Serum ADAM10 level was increased in type 1 diabetes and was a significant determinant of circulating cRAGE." (PMID 26325204, 2015). "Serum ADAM10 correlated with serum cRAGE in type 1 diabetes (r = 0.40, p<0.01) and in controls (r = 0.31." (PMID 26325204, 2015). "In addition to having higher serum ADAM10 level, circulating concentrations of sRAGE, esRAGE and cRAGE were also elevated in patients with type 1 diabetes." (PMID 26325204, 2015). "Multiple linear regression analysis was performed to determine whether ADAM10 remained a significant independent determinant of serum cRAGE in patients with type 1 diabetes after adjusting for age, gender, body mass index, smoking status and HbA1c." (PMID 26325204, 2015). "ADAM10 was an independent determinant of serum cRAGE and our data would suggest that the higher concentration of cRAGE in patients with type 1 diabetes might be partly due to the increase in ADAM10." (PMID 26325204, 2015). "Since our in vitro experiments suggest that ADAM10 may play a role in insulin-stimulated RAGE shedding, we have measured serum ADAM10 in a group of type 1 diabetic patients and healthy controls, and evaluated the relationship between ADAM10 and the various soluble RAGE isoforms." (PMID 26325204, 2015). "In the present study, we have further determined the effect of insulin on ADAM10 expression and activity in vitro and evaluated whether there are changes in ADAM10 level in type 1 diabetes and its role in determining levels of circulating soluble RAGE isoforms." (PMID 26325204, 2015). "In keeping with our in vitro data, we have found that ADAM10 level was increased in patients with type 1 diabetes compared to non-diabetic controls." (PMID 26325204, 2015).
abdominal aortic aneurysm (3 papers, 2017 to 2020). Enlargement and ballooning of the vessel that supplies arterial blood to the abdomen, pelvis and legs. "With evidence showing that other ADAMs (ADAM10 and ADAM17) play roles in the development of abdominal aortic aneurysm, a recent study demonstrated that ADAM9 expression was up-regulated in a murine abdominal aortic aneurysm model." (PMID 33096780, 2020). "Moreover, studies of coronary atherosclerosis and abdominal aortic aneurysm showed that miR-103 played a novel role in negatively regulating inflammatory pathways through targeting chemokine (C-C motif) ligand 13 (CCL13) and ADAM metallopeptidase domain 10 (ADAM10) respectively 55,56." (PMID 32549769, 2020).
acute lymphoblastic leukemia (3 papers, 2021 to 2025). Leukemia with an acute onset, characterized by the presence of lymphoblasts in the bone marrow and the peripheral blood. "ADAM10-mediated Notch1 cleavage and shedding in T-cells controls T-cell development, and also contributes to oncogenic Notch signaling by shedding Notch1 mutants in T-cell acute lymphoblastic leukemia (T-ALL)." (PMID 33413403, 2021). "In this study, we investigated the potential roles of ADAM10 and CD58 proteins in acute lymphoblastic leukemia (ALL) and chronic lymphocytic leukemia (CLL), both in their treated and untreated states, by comparing their expression levels to a healthy control group." (PMID 40746920, 2025).
acute myeloid leukemia (3 papers, 2021 to 2024). Acute myeloid leukemia (AML) is a group of neoplasms arising from precursor cells committed to the myeloid cell-line differentiation. "TSPAN3 is known to mediate signal transduction events that regulate the expression of the A disintegrin and metalloproteinase 10 (ADAM10), presenilin and the amyloid precursor protein and the development and progression of acute myelogenous leukemia (AML)." (PMID 35326428, 2022).
alcoholism (3 papers, 2018 to 2024). "The compound disulfiram, which is used for alcohol dependence, can also activate ADAM10 and it has been shown to increase blood levels of ADAM10 mRNA." (PMID 38951839, 2024). "We here searched for approved drugs with inhibitory effects on ADAM10 in vitro, and the anti-alcoholism agent, disulfiram, was identified." (PMID 29721164, 2018). "In this regard, it is encouraging that one group found an approved drug for anti-alcoholism, disulfiram, and showed that it effectively restored mMICA expression by inhibiting ADAM10 and did not have unfavorable off-target effects." (PMID 32245188, 2020).
Anxiety (3 papers, 2017 to 2023). Intense feelings of nervousness, tension, or panic often arise in response to interpersonal stresses. "Long-term video recording revealed that ADAM10 cKO mice exhibited increased self-grooming and tremor-like behavior that might be linked to the pathogenesis of anxiety." (PMID 36550333, 2023). "In the EPM test, compared with WT mice, the percentage of time spent in the open arms of the maze and the percentage of open arm entries (% OAE) were increased in ADAM10 cKO mice, suggesting that ADAM10 cKO mice have anxiety-like properties." (PMID 36550333, 2023). "In chickens, LOC770352 (uncharacterized LOC770352), ADAM10 (ADAM metallopeptidase domain 10) and C1orf107/DIEXF (digestive organ expansion factor homolog, zebrafish) have been newly reported as putative QTGs underlying anxiety behavior." (PMID 29186889, 2017).
Arterial thrombosis (3 papers, 2016 to 2022). The formation of a blood clot inside an artery. "ADAM10 sheds the platelet-activating collagen receptor glycoprotein VI (GPVI), and GPVI deficiency protects against arterial thrombosis in mouse models." (PMID 28620033, 2017). "Theoretically, a therapeutic strategy designed to activate Tspan15/ADAM10 or Tspan33/ADAM10 may provide a novel treatment for arterial thrombosis, since irreversible shedding of GPVI would render platelets non-responsive to collagen." (PMID 35269584, 2022). "The best characterized ADAM10 substrate on platelets is the collagen receptor GPVI, which is emerging as a promising anti-platelet drug target for the treatment of arterial thrombosis." (PMID 26668317, 2016).
Autoimmunity (3 papers, 2017 to 2024). The occurrence of an immune reaction against the organism's own cells or tissues. "This review will focus on characterizing ADAM10 and the potential use of ADAM10 inhibitors in the context of cancer and autoimmunity." (PMID 32265938, 2020). "The overwhelming data in cancer and autoimmunity, even added within the last 5 years implicates ADAM10 in the progression of disease." (PMID 32265938, 2020). "This review goes through the most recent pre-clinical data with inhibitors as well as clinical data supporting the use of ADAM10 inhibitor use in cancer and autoimmunity." (PMID 32265938, 2020). "Shedding by ADAM10 and ADAM17 is a highly regulated mechanism in multiple conditions including inflammation, cancer, and autoimmunity." (PMID 38897568, 2024).
breast tumors (3 papers, 2014 to 2018). "Returning to the role of ADAM10, previous studies have shown that higher pre-treatment expression of ADAM10 in breast tumors correlates with decreased clinical response of patients to trastuzumab and poorer relapse-free survival." (PMID 30458861, 2018).
chronic kidney disease (3 papers, 2018 to 2024). Impairment of the renal function secondary to chronic kidney damage persisting for three or more months. "In a rat model of chronic kidney diseases, increased expression of ADAM10 contributed to epithelial-to-mesenchymal transition of tubular epithelia and increased kidney fibrosis." (PMID 39448683, 2024). "ADAM10 expression was also assessed in kidneys from patients with chronic kidney disease (CKD)." (PMID 30117015, 2018).
epileptic seizures (3 papers, 2016 to 2019). "Based on the biological effects of its substrates, the potential pathogenic roles of ADAM10 in epileptic seizures can be classified into amyloidogenic processes in the ageing stage and cortical dysplasia in the developmental stage." (PMID 31087543, 2019). "Current data regarding ADAM10 in epileptic seizures were collected and reviewed for potential pathogenic roles (ie amyloidogenic processes and cortical dysplasia) and regulatory mechanisms (ie transcriptional and posttranscriptional regulation)." (PMID 31087543, 2019). "Based on the protective effects of ADAM10 against epileptic seizures, this study was designed to investigate the association between ADAM10 and TLE from a genetic perspective." (PMID 27445971, 2016). "Hence, this review discusses the current evidence for the role of ADAM10 in epileptic seizures." (PMID 31087543, 2019).